HMGB1 (high mobility group box 1)
Diseases named in the same sentence as HMGB1 in open-access papers (continued):
Sharing a sentence is not in itself a finding about the gene and the disease.
Arthritis (continued). "In previous investigations, administration of PDRN down-regulated the expression of the inflammatory cytokine HMGB-1 in arthritis and periodontitis models." (PMID 28771195, 2017). "In fact, several data demonstrated that, together with the commonly used monoclonal antibody-based therapies, monoclonal antibodies directed versus HMGB1 can protect against arthritis in experimental models." (PMID 29200665, 2017). "It is present in excessive levels in joints and serum of RA patients, and antagonistic HMGB1 therapies ameliorate arthritis in murine models." (PMID 27446084, 2016). "Our results showed that rTMD1 treatment significantly reduced the paw thickness, arthritis score, and levels of serum HMGB1." (PMID 27311356, 2016). "HMGB1, a nuclear protein released from stressed cells, has been indicated as a bone-active cytokine and involved in ossification, arthritis and ectopic mineralization pathogenesis." (PMID 27243975, 2016). "Another study on rat and mouse models proved HMGB1 antibodies to reduce histologic severity of RA, correlating with the mean arthritis score." (PMID 26854151, 2015). "In a rat model with artificially induced arthritis, HMGB1 was detected in all nuclear, cytoplasmic and extracellular compartments while it was restrained in the nucleus in healthy controls." (PMID 26854151, 2015). "Previously, HMGB1 was identified as a cytokine mediator for lethal systemic inflammation, arthritis and local inflammation." (PMID 23737912, 2013). "Although the linkage between hypoxia and inflammation is not clear, the possibility that tissue hypoxia and its resultant extracellular high mobility group box 1 (HMGB1) play an important role in arthritis development has been indicated." (PMID 23834772, 2013). "Increasing evidence indicated that HMGB1 acts as an early inflammatory mediator in the pathogenesis of arthritis." (PMID 22110531, 2012). "In rat models, HMGB-1-blocking antibodies reversed arthritis and produced remarkably improved, durable survival despite delayed intervention following induction of septic shock by cecal ligation and puncture." (PMID 22916155, 2012). "These experiments have enabled us to propose a mechanism by which HMGB1 contributes to both inflammatory and destructive processes activated during arthritis." (PMID 21871094, 2011). "Through this study we have increased knowledge of the proinflammatory functions of HMGB1 in arthritis in both RA and OA settings." (PMID 21871094, 2011). "This becomes especially important because C5L2 is required for the release of high mobility group box 1 protein (HMGB1) that has been shown to have an important role in the pathogenesis of arthritis." (PMID 20975959, 2010). "Combined with our previous study, we suggest that HMGB1-triggered arthritis is probably mediated through IL-1 activation." (PMID 18582368, 2008). "Our study demonstrates a novel strategy of treatment of arthritis by nuclear sequestration of HMGB1 thereby preventing HMGB1 release." (PMID 18179697, 2008). "Increased levels of HMGB1 are found in the joints of rheumatoid arthritis patients, and the protein triggers arthritis when applied into the joints of naïve mice." (PMID 18582368, 2008). "Our results show that pathways other than TNFα are involved in the initiation of joint inflammation in the case of HMGB1-induced arthritis." (PMID 18582368, 2008). "TNF and IL-1β, pivotal cytokines in arthritis pathogenesis, both have the ability to induce the release of HMGB1 from myeloid and dendritic cells." (PMID 18346273, 2008). "Intraperitoneal injections of oxaliplatin in early collagen type II-induced arthritis trapped HMGB1 with a distinct biphasic response pattern." (PMID 18179697, 2008). "A number of published observations have demonstrated that the pro-inflammatory mediator HMGB1 has a functional impact on the pathogenesis of arthritis." (PMID 18346273, 2008).
Arthritis (continued). "Failure of oxaplatin-mediated protection from arthritis at this late phase of disease thus coincided with extensive extracellular HMGB1 presence." (PMID 18179697, 2008). "Therapy based on HMGB1 antagonists has shown encouraging results in experimental arthritis and warrants further scientific exploration using independent methods." (PMID 18179697, 2008). "We have previously shown that the overall frequency and severity of HMGB1-induced arthritis varies between different mouse strains." (PMID 18582368, 2008). "High-mobility group box chromosomal protein 1 (HMGB1) has recently been identified as an endogenous mediator of arthritis." (PMID 18346273, 2008). "Short-term oxaliplatin treatment in collagen type-II-induced arthritis was recently studied in mice and beneficial therapeutic effects coinciding with nuclear HMGB1 retention were noted." (PMID 18346273, 2008). "We and others have demonstrated local overexpression of cytoplasmic and extracellular HMGB1 in synovial biopsy specimens in RA and experimental arthritis." (PMID 17397533, 2007). "In the present study, we demonstrate that cytoplasmic and extracellular HMGB1 appears early in the development of arthritis." (PMID 17397533, 2007). "In advanced arthritis, the number of cells with cytoplasmic HMGB1 expression was quantitatively comparable to that of cells expressing TNF and IL-1β." (PMID 17397533, 2007). "Intra-articular injection of HMGB1 in mice induces arthritis, and treatment with HMGB1 antagonist attenuates collagen-induced arthritis (CIA) in rats and mice." (PMID 17397533, 2007). "We have demonstrated that extranuclear HMGB1 appears early in disease progression and is abundantly expressed in advanced arthritis." (PMID 17397533, 2007). "HMGB1 is a potent trigger of arthritis and its expression is increased in synovial tissue of RA patients as well as in experimental arthritis." (PMID 15987483, 2005). "It has also been reported that quercetin could attenuate arthritis by targeting the HMGB1/TLR4/p38/ERK1/2/NF-κB p65 pathway in mice." (PMID 38927100, 2024). "Regarding different clinical manifestations, logistic regression identified that serum concentrations of Gd-IgA1 (CI 0.943–0.992, p = 0.028), RAGE (CI 0.983–0.998, p = 0.026) and PCDH1 (CI 1.021–1.137, p = 0.012), and urinary HMGB1 (CI 1.000–1.002, p = 0.026) are predictors of arthritis in IgAV." (PMID 38673968, 2024). "In 2002, the research group of Kokkola first reported that HMGB1 was upregulated in the nucleus, cytoplasm, and extracellular environment of the synovial tissue (ST) and synovial cells in patients with RA and experimental arthritis rat models." (PMID 37667233, 2023). "HMGB1 is a coupling factor for hypoxia and inflammation in arthritis." (PMID 33925132, 2021). "In this review, we summarize recent evidence showing that neuronal HMGB1 is required for the development of neuroinflammation, as knock out limited to neurons or its neutralization via antibodies ameliorate injury in models of nerve injury and of arthritis." (PMID 34685772, 2021). "In this study, we found that peripheral HMGB1 contributes to arthritis-induced pain." (PMID 32796317, 2021). "Recent studies showed that HMGB1 could promote the pathogenesis of inflammatory diseases including arthritis." (PMID 32575510, 2020). "Neutralizing antibodies against HMGB1 have been used to confirm its involvement in mouse models of various pathologies, such as arthritis, suggesting that HMGB1-neutralizing antibodies could be used therapeutically." (PMID 32587593, 2020). "Hypoxia induces MAPK activity in rat NPCs, and hypoxia is also a potent inducer of extracellular HMGB1 and may, in turn, play an important role in the development of arthritis." (PMID 30704538, 2019).
Arthritis (continued). "In particular, in two notably different models of arthritis, collagen-induced arthritis (CIA) and a genetic model of arthritis, Schierbeck and colleagues demonstrated that anti-HMGB1 monoclonal antibody administration significantly ameliorated the clinical courses in these experimental conditions." (PMID 29200665, 2017). "Furthermore, direct injection of HMGB1 into murine knee joints initiated persistent inflammatory responses and synovitis and antagonistic HMGB1 therapies ameliorated arthritis." (PMID 27446084, 2016). "For example, sRAGE is found to interact with Mac-1 in an HMGB1-induced arthritis model." (PMID 27688824, 2016). "To elucidate whether HMGB1 could contribute to the inflammatory process seen in arthritis via the induction of PGE2 synthesis, we investigated the effect of IL-1βlow/HMGB1 complexes on synovial fibroblasts." (PMID 23488692, 2013). "Similarly, HMGB1 blockade ameliorates arthritis in animals, while its administration in the joints induces arthritis." (PMID 23772226, 2013). "Furthermore, there is abundant evidence that blockade of extracellular HMGB1 suppresses disease progression in experimental arthritis." (PMID 24302816, 2013). "Increased HMGB1 was found in the joints of RA patients, and the HMGB1 transferred into health mouse joint could induce the arthritis." (PMID 22110531, 2012). "The data presented in this paper together with earlier studies on the interaction of HMGB1 with different TLR-ligands suggest that HMGB1 might be a unifying factor for the contribution of various infections to arthritis pathogenesis." (PMID 21871094, 2011). "Herein we reveal a mechanism by which HMGB1 may contribute to both inflammatory and destructive processes present during arthritis." (PMID 21871094, 2011). "Extracellular HMGB1 is abundant in arthritic joint tissue where it is suggested to promote inflammation as intra-articular injections of HMGB1 induce synovitis in mice and HMGB1 neutralizing therapy suppresses development of experimental arthritis." (PMID 21871094, 2011). "Even though it has not been directly involved in the pathogenesis of gout, HMGB1 is implicated in the pathomechanism of rheumatoid and experimental arthritis, suggesting a possible role in the induction of gouty arthritis." (PMID 22195044, 2011). "In the present study we demonstrate that HMGB1-triggered joint inflammation is not mediated via the TNF pathway since the arthritis incidence and severity remained similar in mice deficient for TNFα and in backcrossed C57Bl6 control animals." (PMID 18582368, 2008). "This theory is also supported by the fact that intra-articular HMGB1 injections cause arthritis in wild-type mice but not in IL-1 type I-receptor deficient mice." (PMID 18346273, 2008). "In our previous study, we demonstrated that mice deficient for IL-1 receptor did not develop arthritis upon intraarticular administration of HMGB1." (PMID 18582368, 2008). "Recent findings have suggested that the high-mobility group box chromosomal protein 1 (HMGB1) might be an important molecule in the pathogenesis of arthritis." (PMID 18346273, 2008). "Recent evidence implicates a role for HMGB1 in the pathogenesis of arthritis." (PMID 17397533, 2007). "In addition, at the time point of arthritis onset, a substantial number of the infiltrating inflammatory cells expressed HMGB1 in their cytoplasm, apparently more than cells expressing TNF or IL-1β." (PMID 17397533, 2007). "Moreover, pharmacological inhibition of spinal HMGB1 signaling reverses arthritis pain." (PMID 39439003, 2024). "Four proteases associated with arthritis, neutrophil-derived human elastase (HNE) and Cathepsin G (CG), fibroblast-derived matrix metalloproteinase 3 (MMP-3) and the serine protease dipeptidyl peptidase-IV (DPP-IV), were investigated for their ability to process HMGB1." (PMID 33391251, 2020). "Moreover, HMGB1 blockade reduces arthritis induction in experimental models." (PMID 29200665, 2017).
Arthritis (continued). "Whether HMGB1-induced arthritis is mediated via the TNFα pathway, however, is unknown." (PMID 18582368, 2008). "Recombinant IL-1α, HMGB1 and S100A9 exhibited immune adjuvant activity, increased the overall incidence of arthritis and induced an inflammatory response in the lung in mouse models, respectively." (PMID 40216765, 2025). "Consistent with previous knowledge, levels of serum HMGB1 were significantly higher in children with systemic JIA versus healthy controls and other types of arthritis in our study." (PMID 34247641, 2021). "Together, our study demonstrates the important aspects of sex and cellular location in the contribution of peripheral HMGB1 and TLR4 to arthritis-induced pain." (PMID 32796317, 2021). "The purpose of this study is to investigate the role of TREM-1, HMGB-1, and RAGE in shoulder tendon tissues and systemic circulation in the setting of glenohumeral arthritis." (PMID 27792788, 2016). "We aimed to investigate the effects of IL-1β/HMGB1 complexes on mPGES-1 and other enzymes of the PGE2 pathway in synovial fibroblasts (SFs) from patients with arthritis." (PMID 23488692, 2013). "High mobility group box 1 (HMGB1), a highly conserved, ubiquitous protein, is released into the circulation during sterile inflammation (e.g. arthritis, trauma) and circulatory shock." (PMID 23799067, 2013). "Patients with inflammatory arthritis had lower muscular HMGB1 staining than those without arthritis (p < 0.05)." (PMID 32363191, 2020). "Since the first studies by Andersson and coworkers, it has been clarified that HMGB1 can stimulate the release of IL-1, IL-6, and TNF-α and it determines the beginning and the development of inflammation in different experimental models of arthritis." (PMID 29200665, 2017). "Apart from DAMPs like HMGB1, RAGE also binds with advanced glycation end products (AGEs) and RAGE activation plays a significant role in the progression of inflammatory diseases like arthritis." (PMID 27792788, 2016). "The abundant extranuclear HMGB1 protein expression throughout the inflamed synovium in advanced arthritis, however, was not accompanied by an overall upregulation of HMGB1 mRNA." (PMID 17397533, 2007). "Another possibility to explain the lack of correlation between the clinical course and HMGB1 expression following infliximab treatment could be that HMGB1 may be more dependent on the IL-1 pathway than the TNF pathway in the pathogenesis of arthritis." (PMID 18346273, 2008). "While the HMGB-1-responsive cells were not identified, involvement of macrophages, which express HMGB-1 receptors and play important roles in the development of arthritis appears likely." (PMID 37006298, 2023).
injury (88 papers, 2007 to 2025). Damage inflicted on the body as the direct or indirect result of an external force, with or without disruption of structural continuity. "The serum levels of both NLRP3 and HMGB-1 were independent risk factors for 6-month mortality in severe blunt abdominal trauma patients." (PMID 31411276, 2019). "It has been reported that HMGB1 is positively associated with changes in LOX-1, IL-1β, and TNF-α in murine models of COPD and acute lung injury." (PMID 38655086, 2024). "The translocation and release of High Mobility Group Protein 1 (HMGB1) play important roles in inflammatory response in neonatal HI brain injury." (PMID 39496476, 2024). "The DAMP molecule HMGB1 was present in BEVs isolated from the plasma of rats after traumatic brain injury." (PMID 38383487, 2024). "Among patients with HBV-ACLF, high levels of HMGB1 correlate closely with coagulation and brain injury." (PMID 36712653, 2022). "Recent study reveals that GLY inhibits the activation of HMGB1/TLR4/NFκb signal pathway in radiation-induced acute lung injury." (PMID 35586052, 2022). "TNF-α/HMGB1 (high mobility group box 1) inflammation signaling pathway regulates pyroptosis during acute liver failure and kidney injury." (PMID 35646948, 2022). "In this study, we demonstrate that inhaled [D-Ala2]-dynorphin 1-6 (leytragin), a peptide agonist of δ-opioid receptors, significantly inhibits HMGB1 secretion in mice with lipopolysaccharide- (LPS-) induced acute lung injury." (PMID 34616852, 2021). "High-mobility group box-1 (HMGB1), ATP and S100 proteins are the most common DAMPs that critically influence immune response after brain injury." (PMID 34572077, 2021). "It is likely that high-mobility group box 1 (HMGB1) is released after ischemic renal injury, which further promotes active MΦ recruitment." (PMID 34445160, 2021). "The role of airway HMGB1 in the pathogenesis of ALI was further validated using anti-HMGB1 antibodies in a mouse model of hyperoxia-induced acute lung injury." (PMID 32024151, 2020). "A growing body of evidence shows the beneficial role of interfering with HMGB-1 effects after brain injury." (PMID 31507379, 2019). "We have therefore also investigated HMGB1 concentrations in plasma derived from simultaneously acquired arterial and venous samples in trauma patients." (PMID 31892315, 2019). "Effects of long-term storage and freeze/thaw cycles on HMGB1 plasma concentration were assessed through reanalysis of 24 plasma samples from five trauma patients." (PMID 31892315, 2019). "With the addition of full-length K18, caspase-cleaved K18, and HMGB1, ten (77%) of 13 patients with subsequent acute liver injury were correctly identified at first presentation." (PMID 29146439, 2018). "With the addition of full-length K18, caspase-cleaved K18, and HMGB1, 49 (98%) of 50 patients with acute liver injury were correctly identified at first presentation." (PMID 29146439, 2018). "This is in concordance with the demonstration of HMGB1 as an early mediator of inflammation following acute, local organ injury in liver ischemia reperfusion as well as in post-ischemic brain injury." (PMID 17397533, 2007). "Based on previous research, we hypothesized that HMGB1 plays a pivotal role in GEF-induced liver injury." (PMID 40932871, 2025). "The damaged liver releases HMGB1, which binds to its receptors, and this subsequently activates signaling pathways, leading to the secretion of proinflammatory cytokines including TNF-α, which causes acute liver injury." (PMID 37511276, 2023). "This may partially explain the potential material basis of JDNW ameliorating ACLF liver injury by reducing oxidative stress and apoptosis by inhibiting the HMGB1/TLR-4/NF-κB pathway." (PMID 35873636, 2022).